GLP1R (glucagon like peptide 1 receptor)
Diseases named in the same sentence as GLP1R in open-access papers (continued):
Sharing a sentence is not in itself a finding about the gene and the disease.
metabolic dysfunction-associated steatohepatitis (34 papers, 2018 to 2026). Metabolic dysfunction-associated steatohepatitis (MASH, formerly known as nonalcoholic steatohepatitis or NASH) is a type of fatty liver disease. "GLP-1R agonists further attenuate hepatic steatosis and inflammation in models of non-alcoholic steatohepatitis (NASH), alleviating hepatocyte injury." (PMID 41573745, 2025). "GLP-1R is a popular receptor target in endocrine diseases, non-alcoholic steatohepatitis, tumors, and other areas." (PMID 37780209, 2023). "A similar dual GLP-1R/GCGR agonist is MEDI0382, also known as cotadutite, which is under development for T2DM comorbidities, nonalcoholic steatohepatitis (NASH), and chronic kidney disease." (PMID 36145148, 2022).
endothelial dysfunction (31 papers, 2010 to 2026). In vascular diseases, endothelial dysfunction is a systemic pathological state of the endothelium (the inner lining of blood vessels) and can be broadly defined as an imbalance between vasodilating and vasoconstricting substances produced by (or acting on) the endothelium. "Finally, P5P reversed the beneficial impact of 1,25-D3 on neurological injury and endothelial dysfunction by modifying the expression of inflammatory and vascular protection factor-associated proteins such as GLP-1R, VEGF-α, e-NOS, ICAM-1, and VCAM-1." (PMID 40224490, 2025). "At least 1 study showed that liraglutide treatment of mice with arterial hypertension normalized blood pressure, cardiac hypertrophy, vascular fibrosis, endothelial dysfunction, oxidative stress, and vascular inflammation in a GLP-1R-dependent manner." (PMID 40803202, 2025). "Collectively, these in vitro findings suggest that liraglutide alleviates ox-LDL-induced endothelial dysfunction through GLP-1R-dependent down-regulation of the LOX-1/NOX4/NF-κB signaling pathway." (PMID 37278349, 2023). "Liraglutide improved oxidized LDL-induced endothelial dysfunction via GLP-1R-dependent downregulation of LOX-1-mediated oxidative stress and inflammation." (PMID 37278349, 2023). "In recent years, mounting evidence has reported the protective effects of GLP-1R agonists against endothelial dysfunction." (PMID 37278349, 2023). "In ex vivo studies on diabetic patients, exenatide increased eNOS activation and NO production in ECs and reduced HG- or lipid-induced endothelial dysfunction in arterioles, both through GLP-1R and AMPK activation." (PMID 36140374, 2022). "Liraglutide treatment also alleviated vascular fibrosis, inflammation, oxidative stress, and endothelial dysfunction via GLP-1R in hypertension." (PMID 36225176, 2022). "New antihyperglycemic agents including glucagon-like peptide-1 receptor agonists and the sodium–glucose cotransporter-2 inhibitors (SGLT2i) have been shown to attenuate endothelial dysfunction at the cellular level." (PMID 34884494, 2021). "However, few articles have investigated the effects of GLP-1R on ox-LDL-induced LOX-1-mediated endothelial dysfunction." (PMID 37278349, 2023). "Recent studies have indicated that the protective properties against endothelial dysfunction, anti-inflammatory effects on macrophages and the anti-proliferative action on smooth muscle cells may contribute to atheroprotection through GLP-1R signaling." (PMID 34131405, 2021). "Therefore, in this study, we aimed to investigate the effects of liraglutide on endothelial dysfunction in LDL receptor-deficient mice and ox-LDL-challenged human umbilical vein endothelial cells (HUVECs) and to explore the role of GLP-1R and LOX-1 in this process." (PMID 37278349, 2023). "In a murine model of arterial hypertension, liraglutide, a GLP-1RA, normalizes blood pressure, cardiac hypertrophy, vascular fibrosis, endothelial dysfunction, oxidative stress and vascular inflammation through the GLP-1/GLP-1R axis." (PMID 40592472, 2025). "The beneficial effects of glucagon-like peptide 1-receptor agonists (GLP-1RA) in reducing oxidative stress may be based in part on inhibition of NOX2 in inflammatory monocytes of hypertensive mice, which trigger endothelial dysfunction." (PMID 40803202, 2025). "GLP-1, however, engages the GLP-1R/ERK1/2/HDAC6 axis to modulate downstream transcriptional activity, it lowers intracellular ROS, reduces Akt and ERK1/2 phosphorylation, restores HDAC6 expression, and thereby alleviates endothelial dysfunction and excessive autophagy." (PMID 41019986, 2025). "However, none of these studies have elucidated the potential role of GLP-1R and LOX-1 in the protection of liraglutide against endothelial dysfunction." (PMID 37278349, 2023).
thyroid cancer (30 papers, 2012 to 2026). "Following the Silverii study was a meta-analysis that reported a 62% excess risk for thyroid cancer after GLP-1R agonist exposure." (PMID 41178720, 2025). "Glucagon-like peptide 1 receptor agonist therapy is associated with lower risks of several cancers (e.g., prostate, lung, and colon cancer) and a higher risk of thyroid cancer." (PMID 40361502, 2025). "In contrast to concerns raised in the broader literature, our study found that higher GLP1R expression was associated with substantially better survival in patients with thyroid carcinoma." (PMID 39777709, 2025). "As an alarming finding, the activation of GLP-1R has been associated with developing thyroid cancer." (PMID 38801466, 2024). "In an epidemiologic analysis integrating data from the Thyroid Cancer Genome Atlas project and The Genotype-Tissue Expression repository, increased GLP-1R expression was linked to improved survival in patients with thyroid cancer (hazard ratio: 0.42, logrank P = .021)." (PMID 41376649, 2026). "The use of glucagon-like peptide-1 receptor (GLP-1R) agonists such as semaglutide, a novel class of antidiabetic medications, has raised concerns about potential adverse effects, particularly a possible association with thyroid cancer (TC)." (PMID 39908200, 2025). "Our findings reveal that increased GLP1R expression is associated with improved overall survival in cancers such as bladder cancer, breast cancer, esophageal adenocarcinoma, renal clear cell carcinoma, and thyroid carcinoma." (PMID 39777709, 2025). "Our findings demonstrate that increased GLP1R expression is associated with improved overall survival in certain cancers, such as bladder cancer, breast cancer, esophageal adenocarcinoma, renal clear cell carcinoma, and thyroid carcinoma." (PMID 39777709, 2025). "Therefore, the risk of thyroid cancer associated with incretin-based therapies is controversial and may differ between GLP-1R agonists and DPP-4 inhibitors or among different DPP-4 inhibitors." (PMID 27029076, 2016). "Further, GLP-1R expression levels stratified TCGA thyroid cancers into unique immunogenetic transcriptional profiles." (PMID 42294299, 2026). "Based on a range of analysis approaches and data sources, debates continue about the long-term safety of GLP-1R agonists in some patients, with thyroid cancer as one focus of the discussion." (PMID 41178720, 2025). "High GLP-1R levels in tumors predicted longer overall survival of patients with bladder, breast, esophageal adenocarcinoma, renal clear cell, and thyroid cancers." (PMID 41178720, 2025). "There is a notable increase in thyroid cancer with the use of GLP-1R agonists, including semaglutide." (PMID 38801466, 2024). "With respect to risk of MTC with GLP-1 receptor agonists, data have been mixed regarding expression of GLP-1R in healthy human thyroid and human thyroid cancers." (PMID 35158824, 2022). "As GLP-1R agonist therapies continue to expand in clinical use, further investigation is warranted to determine the oncogenic implications of this overexpression for thyroid cancer." (PMID 42294299, 2026). "Additionally, GLP1R agonist Liraglutide has been shown to inhibit proliferation and migration in thyroid cancer cells via the PI3K/Akt/mTOR pathway." (PMID 40696350, 2025). "In patients, a retrospective study based on FAERS data reported that GLP-1R agonist use was associated with an excess risk of thyroid cancer, while metformin use was not." (PMID 41178720, 2025). "When a random-effect model was applied, the association between GLP-1R therapy use and thyroid cancer was not significant." (PMID 41178720, 2025). "This could imply a potential protective role of GLP1R in the context of established thyroid cancer, possibly by modulating tumor behavior or enhancing the efficacy of treatment." (PMID 39777709, 2025). "The use of GLP-1R agonists increases calcitonin gene-related peptide (CGRP) in thyroid cancer." (PMID 38801466, 2024).
thyroid cancer (continued). "However, the exact mechanisms underlying this relationship remain unclear, and further research is needed to fully understand how GLP1R expression influences thyroid cancer progression and survival." (PMID 39777709, 2025). "However, whether Semaglutide’s effect is mitigating or exacerbating remains unclear, emphasizing the necessity for further research on the outcome of GLP-1R agonists on cancer, specifically thyroid cancer." (PMID 38801466, 2024). "Contrarily, other studies have indicated that GLP-1R agonists do not affect the growth or survival of human pancreatic, colon, or thyroid cancer cells." (PMID 39777709, 2025). "The relationship between GLP-1R agonists and tumor growth is not well defined; studies have shown that for some tumors, such as liver cancer, GLP-1R agonists inhibit their growth, but for others, such as thyroid cancer, GLP-1R agonists actually accelerate their growth." (PMID 39858999, 2024).
alcohol use disorder (29 papers, 2015 to 2026). "First, we tested whether genetic variation in GLP1R is associated with AUD in participants enrolled at the National Institute on Alcohol Abuse and Alcoholism Laboratory of Clinical and Translational Studies (LCTS)." (PMID 26080318, 2015). "This narrative review evaluates glucagon-like peptide-1 receptor agonists (GLP-1RAs) as potential treatments for alcohol use disorder (AUD), a major public health problem with limited treatment options." (PMID 42144979, 2026). "The effects of GLP1R agonists in Alcohol Use Disorder (AUD) and substance use disorder (SUD) are mediated, in part, through the downregulation of dopamine signaling." (PMID 39865816, 2025). "Are glucagon-like peptide-1 receptor (GLP-1) agonists effective in the treatment of alcohol use disorder?" (PMID 39535805, 2025). "Preclinical studies have identified glucagon-like peptide-1 receptor (GLP-1R) agonists, and the antismoking agents varenicline and bupropion as tentative agents for treatment of alcohol use disorder (AUD)." (PMID 37719854, 2023). "When tentatively treating individuals with alcohol use disorder using GLP-1R agonists, it is important to take into account the potential aversive effects." (PMID 37063267, 2023). "Accordingly, the GLP-1 receptor (GLP-1R) has begun to be studied as a potential pharmacotherapeutic target for alcohol use disorder (AUD)." (PMID 35906358, 2022). "This systematic review and meta-analysis explored the potential of glucagon-like peptide-1 receptor agonists (GLP-1RAs) in managing alcohol use disorder (AUD), synthesising data from three randomised controlled trials (RCTs) and six observational studies encompassing 2,740,637 participants." (PMID 41350683, 2025). "The present translational study is based on four human genetic association studies and one preclinical study providing data that support the hypothesis that GLP-1R may have a role in the pathophysiology of alcohol use disorder (AUD)." (PMID 26080318, 2015). "The impacts of GLP1R agonists on substance use disorder (SUD) and alcohol use disorder (AUD) are partially mediated by dopamine signaling downregulation." (PMID 39865816, 2025). "In preclinical models of alcohol use disorder (AUD), central GLP-1R activation in reward-related regions such as the VTA and NAc attenuates ethanol intake, conditioned place preference, and stress-induced reinstatement of alcohol-seeking behavior." (PMID 40843757, 2025). "As of 2024, glucagon-like peptide-1 receptor agonists (GLP-1RAs) rank among the top-selling drugs globally and are gaining recognition as potential therapeutic agents for alcohol use disorder (AUD), with growing interest in their roles in modulating alcohol consumption and alcohol craving." (PMID 40722294, 2025).
diabetic retinopathy (29 papers, 2013 to 2026). "Early worsening of diabetic retinopathy (EWDR) has been described during treatment with glucagon-like peptide-1 receptor agonists including subcutaneous semaglutide." (PMID 40637847, 2025). "This cohort study examines the occurrence of diabetic retinopathy, ischemic optic nerve disease, or other ocular complications within 2 years of glucagon-like peptide-1 receptor agonist (GLP-1 RA) use among patients with type 2 diabetes." (PMID 40788647, 2025). "Glucagon-like-peptide 1 receptor (GLP-1R) agonists, like liraglutide, can arrest retinal neurodegeneration promoted by hyperphosphorylated tau in a diabetic retinopathy model via activation of GLP-1R/Akt/GSK3β signaling." (PMID 32231131, 2020). "This discrepancy is likely due to the use of different techniques to detect GLP-1R or, more likely, to differences in the stage of diabetic retinopathy or in the treatment received by the patients." (PMID 31374938, 2019). "Since the retinal pigment epithelium (RPE), that forms the outer retinal barrier, has a key role in protecting from diabetic retinopathy (DR), we investigated the potential expression and function of GLP-1R in a RPE cell line." (PMID 24307763, 2013). "Furthermore, Puddu and Maggi demonstrated that GLP-1R protects the blood-retinal barrier, weakens vascular permeability, and inhibits neuronal apoptosis to protect neural function in diabetes retinopathy." (PMID 40224490, 2025). "Glucagon-like peptide-1 receptor agonists (GLP-1 RAs) are associated with increased risk of diabetic retinopathy (DR) and nonarteritic anterior ischemic optic neuropathy (NAION)." (PMID 40788647, 2025). "Is the use of glucagon-like peptide-1 receptor agonists (GLP-1 RAs) in patients with type 2 diabetes (T2D) associated with an increased risk of sight-threatening diabetic retinopathy (DR) or nonarteritic anterior ischemic optic neuropathy (NAION)?" (PMID 40788647, 2025). "A protective role of sodium–glucose cotransporter 2 inhibitors (SGLT2is) and glucagon-like peptide 1 receptor agonists (GLP1-ra) in the development of diabetic retinopathy and diabetic macular oedema has been described in some recent studies, which may extend beyond glycaemic control." (PMID 38584180, 2024). "Over the past few years, the main argument around ophthalmic involvement and side effects with the use of GLP-1R and GLP-1R-GIPR agonists has been regarding diabetic retinopathy (DR)." (PMID 41464694, 2025). "The possible use of GLP-1, of GLP-1R analogs, or of inhibitors of dipeptidyl peptidase 4 (DPP4, the GLP-1 degrading enzyme) to treat diabetic retinopathy has been investigated in both in vitro and in vivo models." (PMID 31374938, 2019).
polycystic ovary syndrome (29 papers, 2019 to 2026). A disorder that manifests as multiple cysts on the ovaries. "Therefore, GLP-1R agonists, such as liraglutide and dulaglutide, have shown therapeutic potential in PCOS by reducing hyperandrogenemia, improving insulin sensitivity, and promoting weight loss." (PMID 40076938, 2025). "Clinically, there are many therapeutic options for overweight and obese women with PCOS, such as metformin (MET), glucagon-like peptide 1 receptor agonist, and orlistat, which can reduce weight, improve IR, and thus improve hyperandrogenemia and ovulation disorder." (PMID 38374053, 2024). "Both glucagon-like peptide-1 receptor agonists (GLP-1RAs) and metformin (MET) have markedly antiobesity effects in overweight/obese polycystic ovary syndrome (PCOS) patients." (PMID 33679973, 2021).
COVID-19 (27 papers, 2020 to 2025). A disease caused by infection with severe acute respiratory syndrome coronavirus 2. "New evidence with high certainty emerged that glucagon-like peptide-1 receptor agonist (GLP-1RA) use was also associated with a lower risk of COVID-19-related death (SRR 0.83 [95% CI 0.71, 0.97], n=9 studies)." (PMID 37204441, 2023). "On the medication of COVID-19 in diabetes combined with hypertension, GLP-1R agonists, DPP-4 inhibitors, or pioglitazone were associated with significant reductions in hospital admissions, respiratory complications, and mortality, and may improve COVID-19 outcomes in patients with T2DM." (PMID 38144556, 2023). "Although Ang 1-7, the product of ACE2, does not affect intracellular pH, GLP-1R agonists, ACEIs, and ARBs can reduce the progression and damage of COVID-19 by causing a vasodilator and antioxidant effect through activation of the ACE2/Ang 1-7/Mas receptor pathway." (PMID 34285709, 2021). "Effects of sodium-glucose cotransporter 2 inhibitors or glucagon-like peptide-1 receptor agonists on kidney outcomes of COVID-19 patients were not considered." (PMID 40004744, 2025). "Theoretically, some hypoglycemic agents such as glucagon-like peptide-1 receptor agonists (GLP-1RA), dipeptidyl peptidase-4 inhibitors (DPP4i) and a thiazolidinedione (pioglitazone) can improve outcomes in patients with COVID-19 because of their anti-inflammatory effects." (PMID 35246230, 2022). "The clinical course of COVID-19 may also be modulated by the type of antidiabetic drug the patient is receiving, as SGLT2 inhibitors and GLP1R agonists could exacerbate the infection while DPP4 inhibitors may act as mitigators." (PMID 35126141, 2021). "That study suggested metabolic syndrome and NAFLD/NASH available treatments significantly mitigated risks of COVID-19, those with home metformin glucagon-like-peptide 1 receptor agonist (GLP-1 RA) use have a non-significantly reduced odds of hospitalization." (PMID 34565475, 2021). "In this review focused on biguanides, thiazolidinediones, sulfonylureas, dipeptidyl peptidase-4 (DPP4) inhibitors, glucagon-like peptide-1 receptor (GLP-1R) agonists, sodium-glucose cotransporter-2 (SGLT2) inhibitors and insulin, their profiles will be discussed in relation to COVID-19." (PMID 33195481, 2020). "A previous study speculated that GLP-1R agonists did not contribute to the recovery of patients with COVID-19." (PMID 34285709, 2021).
dementia (26 papers, 2014 to 2026). Loss of intellectual abilities interfering with an individual's social and occupational functions. "We also compared the effects of SGLT2is with those of dipeptidyl peptidase-4 inhibitors (DPP-4i) or glucagon-like peptide-1 receptor agonists (GLP-1RA) on dementia incidence." (PMID 41234238, 2025). "Among drug classes, glucagon-like peptide-1 receptor agonists (GLP-1RAs) were associated with a statistically significant reduction in dementia, but not sodium-glucose cotransporter-2 inhibitors (SGLT2is)." (PMID 40193122, 2025). "We also critically analyze the promising field that some anti-T2D drugs may protect against dementia and AD, with a special emphasis on the novel incretin/glucagon-like peptide-1 receptor agonists." (PMID 25071725, 2014). "Many of these organs express GLP-1R, which gives GLP-1 analogue therapies the potential to alleviate the diabetic phenotype systemically and the potential to provide new treatments for other diseases such as dementia and CVD in non-diabetic individuals." (PMID 32269764, 2020).